IL3 (interleukin 3)
Description:
Cytokine secreted predominantly by activated T-lymphocytes as well as mast cells and osteoblastic cells that controls the production and differentiation of hematopoietic progenitor cells into lineage-restricted cells. Also stimulates mature basophils, eosinophils, and monocytes to become functionally activated. In addition, plays an important role in neural cell proliferation and survival. Participates as well in bone homeostasis and inhibits osteoclast differentiation by preventing NF-kappa-B nuclear translocation and activation. Mechanistically, exerts its biological effects through a receptor composed of IL3RA subunit and a signal transducing subunit IL3RB. Receptor stimulation results in the rapid activation of JAK2 kinase activity leading to STAT5-mediated transcriptional program (By similarity). Alternatively, contributes to cell survival under oxidative stress in non-hematopoietic systems by activating pathways mediated by PI3K/AKT and ERK.
Synonyms: IL-3; MCGF; MULTI-CSF; MGC79398; MGC79399
Tractability: Small molecule: a structure with a bound ligand is known. Antibody: its Gene Ontology location is reachable by antibodies, with high confidence; UniProt places it where antibodies can reach, with medium confidence; UniProt predicts a signal peptide or a membrane-spanning region.
Gene: Protein-coding gene on chromosome 5 (132,060,655 to 132,063,204, forward strand). Ensembl gene ENSG00000164399.
Subcellular location: Secreted
Pathways (Reactome):
Immune System: Interleukin receptor SHC signaling; Interleukin-3, Interleukin-5 and GM-CSF signaling
Gene expression (Transcription): RUNX1 regulates transcription of genes involved in interleukin signaling
Signal Transduction: RAF/MAP kinase cascade
Gene Ontology:
Molecular function: cytokine activity; protein binding; interleukin-3 receptor binding; growth factor activity
Biological process: cell surface receptor signaling pathway via STAT; embryonic hemopoiesis; interleukin-3-mediated signaling pathway; positive regulation of cell population proliferation; cell-cell signaling; nervous system development; immune response
Cellular component: extracellular region; interleukin-3 receptor complex
Genetic constraint (gnomAD): Loss-of-function variants: 15 observed, 16.13 expected, observed/expected ratio (o/e) 0.93, 90% interval 0.62 to 1.43. The upper end of that interval is the gene's LOEUF score, 1.43, which puts it in group 5 of 6, group 1 being the genes least tolerant of losing a copy. Missense variants: 162 observed, 202.33 expected, observed/expected ratio (o/e) 0.8, 90% interval 0.7 to 0.91. Synonymous variants: 74 observed, 81.94 expected, observed/expected ratio (o/e) 0.9, 90% interval 0.75 to 1.1.
Homologues: Orthologues: chimpanzee IL3 (98% identical), macaque IL3 (78% identical), mouse Il3 (28% identical), rat Il3 (28% identical).
Diseases named in the same sentence as IL3 in open-access papers:
IL3 is named in the same sentence as 270 diseases in open-access papers, as found by Europe PMC text mining. Sharing a sentence is not in itself a finding about the gene and the disease. The quoted sentences say what the papers report.
Sepsis (47 papers, 2015 to 2025). Sepsis is defined as life-threatening organ dysfunction caused by a dysregulated host response to infection. "For instance, the expansion of HSPCs, as well as myeloid progenitors, is significantly impaired in IL-3-deficient mice during sepsis." (PMID 40376111, 2025). "IL-3 has been associated with immune disorders such as sepsis, colitis, lupus nephritis and arthritis." (PMID 38702781, 2024). "First, we showed that IL-3 is associated with protection against viral pneumonia during sepsis in both humans and mice." (PMID 36911737, 2023). "IL-3 has also been identified as an orchestrator of emergency myelopoiesis during sepsis, where IL-3 deficiency reduced pathological inflammation and injury in mice." (PMID 35145069, 2022). "These capacities were essential when ECLipse was applied to identify sepsis in clinical plasma samples: Measuring multiple host factors (i.e., IL-3, IL-6, and PCT) led to high diagnostic accuracy (AUC = 0.93)." (PMID 36129990, 2022). "In the CLP sepsis model, March3-deficiency increased Il-3-induced serum cytokine levels, and promoted Il-3-amplified inflammatory response and sepsis." (PMID 35075102, 2022). "The authors further tested the prognostic role of IL-3 in two small cohortsof humans with sepsis and found that high plasma IL-3 levels were associated withhigh mortality even after adjusting for disease severity." (PMID 30652781, 2018). "In this study, serum IL-3 concentration was independently associated with all-causehospital mortality in sepsis patients admitted to intensive care." (PMID 30652781, 2018). "Blocking IL-3 production reduces the intensity of sepsis by decreasing inflammation-associated myelopoiesis." (PMID 29209091, 2017). "Additionally, elevated plasma IL-3 levels are associated with increased mortality in human sepsis cases." (PMID 40376111, 2025). "Additionally, IL-3 has recently been implicated in modulating cytokine storm phenomena in sepsis, as it influences myelopoiesis and the corticosteroid response." (PMID 41268545, 2025). "In addition, IL-3 is a cytokine that enhances monocyte differentiation, potentiates cytokine storms in sepsis, and contributes to poor disease outcomes associated with blood infections, including malaria." (PMID 39161730, 2024). "Notably, emergency myelopoiesis is regulated additionally by IL-3, affecting survival during sepsis, and has been linked to occurrence of neutrophil precursor cells in the circulation, visible, for example, in severe-COVID-19 patients." (PMID 35681519, 2022). "Furthermore, it was found that a higher level of IL-3 was associated with a higher rate of mortality in sepsis patients and confirmed that IL-3 plays a major role in immune regulation and higher responses to corticosteroids during sepsis." (PMID 33900481, 2021). "GM-CSF and IL-3 play a central role in the pathogenesis of sepsis and might also be exploited for diagnostic or therapeutic purposes." (PMID 30769926, 2019). "Of note, high plasma levels of IL-3 in sepsis patients are associated with increased mortality." (PMID 30769926, 2019). "Higher levels of IL3 (above 89.4 pg/ml) were associated with poorer prognosis from sepsis." (PMID 29051761, 2017). "Thus, our data confirm the knowledge that pulmonary viral infections during sepsis is associated with increased mortality and suggest that IL-3 may protect within this context." (PMID 36911737, 2023). "IL-3 has been shown to drive emergency hematopoiesis during sepsis and to negatively impact the repopulation capacity of HSCs." (PMID 40569692, 2025). "In sepsis, IL-3 exacerbates acute inflammation by fueling a cytokine storm, and elevated IL-3 levels serve as a predictive indicator of mortality." (PMID 38702781, 2024). "Elevated plasma IL-3 levels in individuals with sepsis are correlated with increased mortality, even after adjusting for prognostic indicators." (PMID 38702781, 2024).
Sepsis (continued). "Our study identifies IL-3 as a predictive disease marker for viral reactivation in sepsis and reveals that IL-3 improves antiviral immunity by enhancing the recruitment and the function of pDCs." (PMID 36911737, 2023). "IL-3 has a dual role in sepsis, stimulating innate immune responses that are detrimental in the acute phase but protective in the immunosuppressive phase by improving antiviral defense mechanisms." (PMID 38114466, 2023). "Interleukin-3 (IL-3) has been identified as an important mediator amplifying acute inflammation in sepsis; however, its function in the host response to viral infections during sepsis remains elusive." (PMID 36911737, 2023). "Collectively, these results suggested that IL-3 enhances antiviral immune responses during sepsis by improving pDC-mediated T cell immunity." (PMID 36911737, 2023). "In sepsis, IL-3 has been described as a central upstream mediator involved in the amplification of the acute phase by inducing emergency haematopoiesis." (PMID 36911737, 2023). "Innate response activator B cells and T cells have been described as the major cellular source of IL-3 in sepsis and SARS-CoV-2 infections, respectively." (PMID 36911737, 2023). "Interleukin 3 (IL-3) is “a cytokine that activates proliferation of hematopoietic stem cells and progenitors, has recently been identified as a key regulator during sepsis pathogenesis." (PMID 36560154, 2022). "Levels of IL-3, another inducer in megakaryocytes production, are also higher in patients with sepsis and correlate with the severity of disease." (PMID 35707370, 2022). "Following sepsis, we tested candidate MK growth factors and observed decreased splenic expression of Tpo, Csf2, and Ccl5, while Il1b was unchanged and Il3 and Il6 were significantly increased." (PMID 35192546, 2022). "In mouse cecal ligation and puncture (CLP) model of sepsis, MARCH3-deficiency facilitates IL-3-ampilfied polymicrobial sepsis." (PMID 35075102, 2022). "During sepsis, megakaryocyte progenitors are mobilized to the spleen, where they differentiate in an IL-3-dependent manner to fully mature megakaryocytes, which then produce a distinct population of CD40Lhi platelets." (PMID 35681519, 2022). "More importantly, in human sepsis, IL-3 aggravates disease exacerbation, and high plasma IL-3 levels are associated with high mortality, even after adjusting for prognostic indicators." (PMID 36425582, 2022). "We stratified patients with sepsis into two groups, IL-3 high versus low, according to the [IL-3] cutoff (=24 pg/ml) from a previous survival study." (PMID 36129990, 2022). "In plasma samples collected at sepsis onset, ECLipse assays reported higher IL-3 concentrations in patients who eventually died of sepsis." (PMID 36129990, 2022). "Recent studies have shown that IL-3 plays an essential role during early sepsis: IL-3 operates upstream of key CKs [e.g., IL-6, IL-1β, and tumor necrosis factor–α (TNF-α)], and high IL-3 levels increase the risk of CK storms." (PMID 36129990, 2022). "IL-3 is a cytokine known for being greatly increased after sepsis and for enhancing BM myelopoiesis." (PMID 35192546, 2022). "IL-3 serum levels also significantly increase during sepsis and drive splenic myelopoiesis in atherosclerotic mice." (PMID 35192546, 2022). "Interleukin-3 (IL-3) is a hematopoietic growth factor and critical regulator of inflammatory response such as sepsis." (PMID 35075102, 2022). "Sepsis provoked an adrenergic-dependent mobilization of megakaryocyte-erythrocyte progenitors (MEPs) from the bone marrow to the spleen, where IL-3 induced their differentiation into megakaryocytes (MKs)." (PMID 35192546, 2022). "At the protein level, plasma Tpo concentrations remained unchanged on post-sepsis day 3, while IL-3 was significantly increased." (PMID 35192546, 2022). "In the cecal ligation and puncture (CLP) model of sepsis, MARCH3-deficiency aggravates IL-3-ampified expression of inflammatory cytokines, organ damage and inflammatory death." (PMID 35075102, 2022).
Sepsis (continued). "This sensing platform was successfully used to detect IL‐3 in blood from people with sepsis and was 5 times faster and 10 times more sensitive than conventional ELISA." (PMID 34766163, 2021). "Studies have shown that IL-3 contributes to emergency myelopoiesis, triggering the expansion of monocytes and neutrophils during sepsis." (PMID 34356636, 2021). "This study identifies and quantifies IL-3 via potentially useful methods and helps in diagnosing sepsis attack." (PMID 33900481, 2021). "Researchers found that the interleukin-3 (IL-3) inflammatory factor is an independent predictor of sepsis attack and death produced by innate response activator (IRA) B cells following Toll-like receptor activation." (PMID 33900481, 2021). "B1 cells derived-IL-3 is considered a critical driving force of sepsis and is responsible for the proliferation and mobilization of neutrophils and inflammatory monocytes." (PMID 33815381, 2021). "For instance, we recently identified that IL-3 amplified acute inflammation in sepsis by fuelling the cytokine storm, with high levels of IL-3 predicting death." (PMID 33602937, 2021). "This role is important considering stress response of myeloid cells as in the case of sepsis, or in the atherogenesis process, as IL-3 stimulates monocytes infiltrating the atherosclerotic plaques." (PMID 33255417, 2020). "We recently published that published that IL-3 has a crucial role in the pathogenesis of the early phase of sepsis." (PMID 29977234, 2018). "Further study proves that interleukin-3 (IL-3) amplifies acute inflammation and plays a critical role in the emergency myelopoiesis of sepsis." (PMID 29228667, 2017). "IL-3 has been previously shown to induce sepsis in mice and it is well-documented that F. tularensis-infected animals eventually die from a cytokine storm." (PMID 27513341, 2016). "Next, we investigated how IL-3 protects against viral pneumonia in sepsis." (PMID 36911737, 2023). "IL-3 may also induce IFNλ expression, an important first-line defence against viruses in the epithelium, as IL-3 and IFNλ expressions are correlated in sepsis and SARS-CoV-2 infections." (PMID 36911737, 2023). "Thus, our results suggest that IL-3 improves local antiviral defence during viral pneumonia in sepsis by increasing pDC numbers in the lungs." (PMID 36911737, 2023). "The aim of our study was to investigate the role of IL-3 during viral infections in sepsis." (PMID 36911737, 2023). "IL-3 promotes myelopoiesis and cytokine storm in cecal ligation and puncture (CLP)-induced acute sepsis, and inhibiting IL-3 activity protected mice from sepsis-induced increases in neutrophils, inflammatory monocytes, and inflammatory cytokines, reducing organ damage and improving survival." (PMID 38114466, 2023). "Collectively, our results suggest that the combination of plasma IL-3 levels and SOFA score may be an early predictive marker to identify patients at risk for virus reactivation during sepsis." (PMID 36911737, 2023). "Although this model might not perfectly reflect the mechanisms regulating virus reactivation, it allowed us to investigate the function of IL-3 during viral pneumonia observed in the immunosuppressive phase of sepsis." (PMID 36911737, 2023). "IL-3 also could protect viral pneumonia in sepsis by promoting the recruitment of circulating plasmacytoid DCs into the lung and T cell initiation." (PMID 38114466, 2023). "The average concentration of each protein was significantly higher in patients with sepsis than in normal controls (P < 0.0001, IL-3; P = 0.0001, IL-6; P < 0.0001, PCT; unpaired two-sided t test), which supported the potential use of these markers for sepsis detection." (PMID 36129990, 2022). "The IL-3/IL-3Rα axis is involved in hematopoiesis, sepsis and several inflammatory disorders, therefore, may serve as targets for development of drugs for the related diseases." (PMID 35075102, 2022).
Sepsis (continued). "Using a mouse model of abdominal sepsis, they showed that IL-3 sourced from IRA B cells induced myelopoiesis of Ly-6Chi monocytes and neutrophils and fueled an uncontrolled cytokine storm; in contrast, IL-3 deficiency protected mice against sepsis." (PMID 36425582, 2022). "To determine whether IL-3 regulates MK maturation in the spleen during sepsis, we treated septic mice with an IL-3–neutralizing antibody or an isotype control antibody." (PMID 35192546, 2022). "Our results indicate that sepsis dramatically increased splenic megakaryopoiesis and platelet production and that splenic MKs and their platelet progeny were unique in both their immune function and their regulation by IL-3." (PMID 35192546, 2022). "We conclude from these results that IL-3 regulates megakaryopoiesis in the spleen during sepsis." (PMID 35192546, 2022). "Anti-interleukin-3 (anti-IL-3) antibody was attached to the zeolite- and iron oxide-complexed capacitance electrode surface through an amine linker to interact with the sepsis biomarker IL-3." (PMID 33900481, 2021). "This study demonstrated the identification of a sepsis biomarker (IL-3) on a capacitance electrode." (PMID 33900481, 2021). "An anti-IL-3 antibody-modified electrode was used to quantify IL-3 and diagnose sepsis attack." (PMID 33900481, 2021). "This experimental method quantifies IL-3 levels and helps diagnose sepsis attacks." (PMID 33900481, 2021). "Recently, the role of IL-3 in sepsis pathogenesis has been investigated." (PMID 34356636, 2021). "The role of IL-3 in sepsis has been less intensively investigated compared to that of GM-CSF." (PMID 30769926, 2019). "Genetic deletion or antibody-mediated blockade of IL-3 activity protects mice from sepsis." (PMID 30769926, 2019). "Despite the low accuracy of IL-3 to predict outcome in sepsis, we furtherevaluated if IL-3 might add to the prognostic information provided by the SOFAscore." (PMID 30652781, 2018). "IL-3 was first reported to be a potential new therapeutic target for sepsis in 2015." (PMID 30373540, 2018). "IL-3 appeared recently as a plausible prognosticmarker in sepsis." (PMID 30652781, 2018). "The roles of IL-3 during the reparative phase of sepsis in mice and human are to be elucidated." (PMID 29977234, 2018). "The study of the role of IL-3 during sepsis is at its very beginning." (PMID 29977234, 2018). "A recent study suggests that IL-3 plays a vital role in sepsis, an infectious disorder." (PMID 30373540, 2018). "IL-3/CD123 axis is suggested as a potential therapeutic target for sepsis." (PMID 30373540, 2018). "Importantly, we showed that during human sepsis, high levels of plasma IL-3 at admission were correlated with a better survival at 28 days after sepsis in two independent cohorts of patients." (PMID 29977234, 2018). "Thus, there is ongoing research for other clinically feasible therapeutic targets (such as IL-3) and medications for human sepsis." (PMID 26257917, 2015). "Thus, IRA B cells and their IL-3 production exacerbate the adverse consequences of sepsis." (PMID 36425582, 2022). "Further clinical study using the IBS platform demonstrated that an IL-3 concentration of > 24 pg mL−1 is critically correlated with the multiorgan failure and mortality of septic patients, suggesting that IL-3 could serve as an independent biomarker to facilitate early warning of sepsis." (PMID 33717630, 2021). "B1a cells are able to secrete IgM as well as immunomodulatory cytokines like IL-10, spontaneously or after infection, and GM-CSF, IL-6, IL-3, TNF; therefore, there is evidence that B1a cells play a protective role in sepsis and survival benefits." (PMID 38474403, 2024). "In a CLP surgery-induced sepsis model of mice, the administration of 5–20 g/kg of the QX1 decoction reduced sepsis-induced upregulated levels of serum IFN-γ, IL-1β, IL-3, IL-6, IL-17, IL-4, IL-10 and TNF-α." (PMID 39051370, 2024).